VDR (vitamin D receptor)
Diseases named in the same sentence as VDR in open-access papers (continued):
Sharing a sentence is not in itself a finding about the gene and the disease.
HCMV infection (4 papers, 2022 to 2024). "Indeed, Snail ablation could moderately increase VDR protein levels in HCMV-infected cells compared to the non-targeting control, suggesting that Snail upregulation might be directly linked to VDR repression during HCMV infection." (PMID 36146811, 2022). "A general reduction in VDR levels has been observed in hematopoietic stem cell transplant patients with active HCMV infection." (PMID 39360328, 2024). "We provide experimental evidence that the expression of VDR on BM-EPCs was significantly reduced in the presence of CMV infection." (PMID 39360328, 2024). "Here, we investigated how the VDR is repressed during HCMV infection, identified potential implications of epigenetic VDR repressors, and discuss potential biological implications of the repression of vitamin D in HCMV-infected cells." (PMID 36146811, 2022). "Since the VDR employs its functions mostly as a heterodimeric holoenzyme with RXRα, we also analyzed RXRα expression in the context of HCMV infection." (PMID 36146811, 2022). "In this study, we established that the VDR is inhibited at the promoter level during HCMV infection." (PMID 36146811, 2022). "HCMV infection makes infected cells refractory to vitamin-D signaling by VDR downregulation, in vitro but also in the blood of hematopoietic stem-cell transplant patients, and hematopoietic cells are a major source of LL-37 production." (PMID 36146811, 2022). "Additionally, we found that the VDR is reduced in peripheral blood of hematopoietic stem cell transplant (HSCT) patients undergoing active HCMV infection." (PMID 36146811, 2022). "Next, we asked whether Snail induction might have a direct effect on VDR expression in the context of HCMV infection." (PMID 36146811, 2022). "Similarly, we aimed to exclude an effect of increased VDR mRNA stability during HCMV infection." (PMID 36146811, 2022). "In contrast, total AMPK protein levels and VDR expression did not change under HCMV infection with or without vitamin D3 treatment." (PMID 35359726, 2022). "In a previous study, we showed that HCMV infection downregulates the VDR and calcitriol (the bioactive form of vitamin D) is not able to directly inhibit HCMV propagation in infected fibroblasts." (PMID 36146811, 2022). "In contrast, YTHDF1-3 expression was increased under HCMV infection but was not affected by vitamin D3, VDR, and AMPK activity." (PMID 35359726, 2022). "Recently, we have shown that HCMV infection downregulates the VDR and that calcitriol and other forms of vitamin D are not able to directly inhibit HCMV AD169 propagation in infected fibroblasts." (PMID 36146811, 2022). "In addition, significantly decreased levels of VDR expression were observed in BM-EPCs with HCMV infection than those without HCMV infection." (PMID 39360328, 2024). "However, no previous studies have focused on the roles of VDR on BM-derived EPCs during CMV infection." (PMID 39360328, 2024). "First, we examined whether AMPK phosphorylation and VDR expression were altered under HCMV infection with or without vitamin D3 treatment." (PMID 35359726, 2022). "Therefore, targeting VDR and p38 MAPK using calcitriol May represent a promising therapeutic approach for augmenting the bone marrow microenvironment in individuals experiencing PGF due to CMV infection." (PMID 39360328, 2024).
head and neck cancer (4 papers, 2022 to 2025). A primary or metastatic malignant neoplasm affecting the head and neck. "The vitamin D receptor (VDR) is expressed in over 400 tissues, including those of the head and neck, implying a potential link between vitamin D and head and neck cancers (HNCs)." (PMID 40218858, 2025). "As knowledge for head and neck cancer (HNC) is limited, we investigated the (pre)clinical and therapeutic relevance of the VDR/VitD-axis." (PMID 36902107, 2023). "Another study examined the influence of genetic sequence variants (GSVs) in the vitamin D3 metabolism pathway, candidate-based GSVs, i.e., VDR, GC, CYP24A1, CYP27A1, CYP27B1, and CYP2R1, on overall survival (OS) and second primary cancer (SPC) in head and neck cancer patients." (PMID 37299554, 2023). "However, to the best of our knowledge, there is no study for head and neck cancers so far showing that overexpression of the VDR correlates with enhanced cisplatin resistance." (PMID 36291915, 2022).
invasive breast carcinoma (4 papers, 2010 to 2025). A carcinoma that infiltrates the breast parenchyma. "Analyses of online databases of 33 human cancers have found increased expression of VDR in invasive breast cancer, serous ovarian adenocarcinoma, and endometrial adenocarcinoma." (PMID 41031356, 2025). "The main purpose of this work was to perform an immunohistochemical study of the expression of the VDR, CYP27B1 and CYP24A1 in a comprehensive series of human breast tissues comprised of normal breast, benign mammary lesions, carcinomas in situ and invasive breast carcinomas." (PMID 20831823, 2010).
juvenile idiopathic arthritis (4 papers, 2020 to 2022). Juvenile idiopathic arthritis (JIA) is the term used to describe a group of inflammatory articular disorders of unknown cause that begin before the age of 16 and last over 6 weeks. "Therefore, low VDR expression is associated with the inflammatory process and plays a potential role in the pathogenesis and prognosis of juvenile rheumatoid arthritis." (PMID 35967569, 2022).
keloid (4 papers, 2021 to 2025). An irregularly shaped, elevated mark on the skin caused by deposits of excessive amounts of collagen during wound healing. "Compared with the White population, Black or African American individuals demonstrated decreased nuclear localization of VDR, which is thought to increase the risk of keloid formation." (PMID 40836860, 2025). "Investigating the local expression and activity of VDR in keloid tissues, as well as the potential impact of VDR polymorphisms, could provide more concrete insights into the mechanisms by which vitamin D influences keloid formation." (PMID 39605169, 2025). "Furthermore, their findings indicated reduced VDR expression in keloid epidermis in comparison to normal skin in keloid patients, which suggests the potential role of vit D deficiency and reduced VDRs in keloid formation." (PMID 39895409, 2025). "Studies have shown that VDR expression is downregulated in keloid fibroblasts compared to normal skin fibroblasts, suggesting an impaired response to vitamin D in keloid tissues." (PMID 39605169, 2025). "Recent studies have explored the potential involvement of vit D and its receptor (VDR) in the intricate process of keloid formation." (PMID 39895409, 2025). "Remarkably, the nuclear localization of VDR increases upon vit D treatment, suggesting its potential application in the treatment of abnormal scarring and the prevention of keloid formation." (PMID 39895409, 2025). "In general, the majority of studies indicate that there is diversity in the expression of VDR, and individuals with keloids often exhibit lower systemic vit D levels." (PMID 39895409, 2025). "The expression and activity of VDR in keloid tissues may be more relevant to the local effects of vitamin D on keloid formation and recurrence than serum levels alone." (PMID 39605169, 2025). "However, literature shows that the nuclear localization of VDR is markedly diminished in the keloid epidermis compared to that in the normal skin." (PMID 39895409, 2025). "Future prospective studies should consider systematic monitoring of vitamin D levels at multiple time points and investigate the impact of vitamin D supplementation, along with evaluation of local vitamin D receptor expression in keloid tissues, to better understand this complex relationship." (PMID 39605169, 2025). "Additionally, genetic variations in the VDR gene may influence individual responses to vitamin D, further complicating the relationship between serum vitamin D levels and keloid recurrence." (PMID 39605169, 2025).
mineral bone disorders (4 papers, 2014 to 2021). "One hundred and forty five patients with CKD stage 3 were genotyped for FokI and BsmI VDR polymorphisms, in order to assess the relationships between these VDR polymorphisms, some markers of mineral bone disorders, and LVH measured by echocardiography." (PMID 24618509, 2014). "Therefore, in line with ongoing efforts to greater understanding of the mechanisms behind racial disparities in markers of CKD- MBD, we aimed to explore the variations in the VDR polymorphisms between black and white African CKD patients and their relationship with markers of mineral bone disorders." (PMID 29415666, 2018).
monocytic leukemia (4 papers, 2013 to 2023). "Changes in VDR levels caused by ATRA have already been described in monocytic leukemia cell lines." (PMID 32916897, 2020). "In this study, we used a FAIRE-seq dataset obtained from THP-1 human monocytic leukemia cells and aligned the resulting peaks with the VDR ChIP-seq dataset from the same cell line." (PMID 24250750, 2013). "On the other hand, one study suggested that only the combined treatment of ATRA and calcitriol effectively increased VDR protein levels but not VDR mRNA expression in the THP-1 human monocytic leukemia cell line." (PMID 32916897, 2020).
Mycobacterium infection (4 papers, 2013 to 2023). Infections with bacteria of the genus Mycobacterium. "Of note, human VDR carrying the t allele of the TaqI VDR polymorphism or the f allele of the FokI VDR polymorphism associates with different or even opposite performance in Mycobacterium infection." (PMID 35991038, 2022). "Studies on vitamin D receptor (VDR) polymorphisms and mycobacterial infection risk have yielded variable results." (PMID 34835346, 2021). "1,25-dihydroxyvitamin D3, which is the active form of vitamin D, was activated by 1α-hydoxylase that was expressed by macrophages and other immune cells and bind to the vitamin D receptor (VDR) for to modulate the immune system in fighting with Mycobacterium infection." (PMID 24349552, 2013).
myeloid leukemia (4 papers, 2013 to 2021). A clonal proliferation of myeloid cells and their precursors in the bone marrow, peripheral blood, and spleen. "Moreover, a study on myeloid leukemia cell lines showed that the most important isoform of RAR involved in the regulation of VDR transcription is RARα." (PMID 32916897, 2020).
osteomyelitis (4 papers, 2021 to 2024). An acute or chronic inflammation of the bone and its structures due to infection with pyogenic bacteria. "In the case of osteomyelitis, key SNPs within genes such as IL-1β (including rs1143634 and rs16944), IL-6 (e.g., rs1800795), VDR, and TNF-α are instrumental in evaluating susceptibility." (PMID 39301021, 2024). "Multivariate regression analysis showed that low level of serum 25(OH)VD and VDR expression were independent risk factors for foot ulcer with osteomyelitis." (PMID 36829206, 2023). "This study aimed to analyze potential associations between VDR genetic variations and susceptibility to extremity osteomyelitis (OM) in a Chinese Han population and investigate potential mechanisms." (PMID 35957979, 2022). "Therefore, people having the C allele in the VDR gene polymorphisms rs731236 and rs2228570 were more likely to develop osteomyelitis." (PMID 39301021, 2024). "Although some studies have confirmed that vitamin D and VDR play a role in the pathogenesis of osteomyelitis, further studies are warranted to elucidate the mechanism of 25(OH)VD and VDR involved in the occurrence of DFO." (PMID 36829206, 2023). "The findings suggest potential linkages between SNPs in genes such as IL-1, IL-6, IFN-γ, TNF-α, VDR, tPA, CTSG, COX-2, MMP1, SLC11A1, Bax, NOS2, and NLRP3 with the development of osteomyelitis." (PMID 39301021, 2024). "Current research has amassed increasing evidence suggesting that SNPs in various genes, including IL-1, IL-6, IFN-γ, TNF-α, VDR, tPA, CTSG, COX-2, MMP1, SLC11A1, Bax, NOS2, and NLRP3, may contribute to the development of osteomyelitis." (PMID 39301021, 2024).
Peritoneal Fibrosis (4 papers, 2014 to 2025). Disorder characterized by a wide range of structural changes in PERITONEUM, resulting from fibrogenic or inflammatory processes. "Functional enrichment analysis highlighted the involvement of extracellular matrix organization, neutrophil degranulation, and the vitamin D receptor (VDR) pathway in peritoneal fibrosis." (PMID 40620673, 2025). "VDR was increased in a mouse model of peritoneal fibrosis and in vitro peritoneal mesothelial cells treated with TGF-β1 and high glucose." (PMID 40620673, 2025). "Paricalcitol, a VDR agonist, has been shown to ameliorate peritoneal fibrosis in a murine model of PD." (PMID 29850544, 2018). "VDR signaling promotes macrophage differentiation into the M2 phenotype, which, as previously demonstrated, is related to peritoneal fibrosis in PD-treated patients." (PMID 25279459, 2014). "The documented role of the VDR pathway in peritoneal fibrosis further underscores its significance." (PMID 40620673, 2025). "VDR signaling could be used to reduce peritoneal fibrosis induced by chronic exposure to PDF as well as surgery-induced adhesion." (PMID 25279459, 2014). "Because inflammation plays an important role in peritoneal fibrosis, vitamin D receptor (VDR) signaling might have a beneficial impact on PDF-induced peritoneal fibrosis." (PMID 25279459, 2014). "However, the results presented here strongly suggest that VDR signaling reduces peritoneal fibrosis through the augment of the number Treg and the downregulation of IL-17 production at peritoneum." (PMID 25279459, 2014). "In conclusion, the activation of immunological regulatory mechanisms by VDR signaling could prevent or reduce fibrosis, as shown in peritoneal fibrosis induced by PDF exposure in mice." (PMID 25279459, 2014). "Furthermore, it was interestingly observed that SAL could enhance VDR expression, highlighting the importance of VDR as a key target in alleviating peritoneal fibrosis." (PMID 40620673, 2025). "VDR is also expressed in macrophages, which could play a role in peritoneal fibrosis." (PMID 25279459, 2014). "VDR partially restored defective autophagy and reduced inflammation in the kidneys of STZ-induced diabetic mice, while autophagy also plays an emerging role in peritoneal fibrosis." (PMID 40620673, 2025). "We investigated whether the intraperitoneal administration of paricalcitol, a specific activator of the VDR, modulates peritoneal dialysis fluid (PDF)-induced peritoneal fibrosis." (PMID 25279459, 2014). "Therefore, at least in our model of PD-treated mice, the evidence suggests that VDR signaling in macrophages might not play a role in the prevention of peritoneal fibrosis." (PMID 25279459, 2014). "Paricalcitol, an analog of vitamin D and a specific activator of vitamin D receptors (VDR), reduced PDF-induced peritoneal fibrosis in murine PD and decreased peritoneal IL-17A levels but not of other cytokines, including IL-1β, IL-2, IL-4, IL-5, IL-6, IL-10, TNF-α, IFN-γ, and TGF-β1." (PMID 32987705, 2020).
renal carcinoma (4 papers, 2010 to 2020). A carcinoma arising from the epithelium of the renal parenchyma or the renal pelvis. "The associations between the VDR gene polymorphisms and breast and renal cancers have been investigated by a number of studies." (PMID 24297042, 2014). "Based on the set of data collected from different studies performed on different ethnic populations, it is not possible to make an authoritative declaration on the role of VDR polymorphisms in breast and renal cancer development and prognosis." (PMID 24297042, 2014). "The kidney is the most vital organ for vitamin D metabolism and calcium homeostasis, though there is still scarcity of data on the association between dietary vitamin D3, VDR gene polymorphism and renal cancer etiology." (PMID 24297042, 2014). "The purpose of this review is to analyze the association of some common VDR gene polymorphisms, such as Taq1, Fok1, Apa1, Bsm1, Cdx2, poly(A) and Bgl1, with breast and renal cancers." (PMID 24297042, 2014). "Males with the VDR A-G-C (rs2254210, rs2853564, and rs4760648) haplotype were at a significantly increased (OR = 1.27; 95%CI = 1.03–1.57) risk of renal cancer compared to males with the most common referent haplotype G-A-T." (PMID 20049159, 2010). "Understanding the role of VDR polymorphisms provides mechanistic insight and may facilitate the development of new preventive strategies for breast and renal cancer." (PMID 24297042, 2014). "Some evidence exists indicating that vitamin D receptor (VDR) gene polymorphisms are associated with both breast and renal cancer; therefore, we put forward the hypothesis that polymorphisms in the VDR gene may influence both the occurrence risks of these cancers and their prognosis." (PMID 24297042, 2014). "(2018) showed that the expression of the calcium channel TRPV5 inversely correlates with the expression of the VDR in renal cancer cells." (PMID 32210800, 2020). "However, data concerning renal cancer are not sufficient to firmly establish the VDR gene polymorphism association." (PMID 24297042, 2014). "We therefore investigated whether common genetic variation in VDR and RXRA, the two genes we observed to be significantly associated with RCC risk, modified associations between renal cancer risk and the frequency of dietary intake of vitamin D and calcium rich foods." (PMID 20049159, 2010). "The inhibition of the TGF-β pathway by 1,25(OH)2D3 and other VDR agonists and the subsequent repression of EMT-TFs and upregulation of epithelial markers have been reported in anaplastic thyroid cancer cells, ovarian cancer cells, lung adenocarcinoma cells and renal carcinoma cells." (PMID 32854355, 2020).
thalassemia (4 papers, 2012 to 2024). An inherited blood disorder characterized by a decreased synthesis of one of the polypeptide chains that form hemoglobin. "Polymorphisms of the vitamin D receptor (VDR) and collagen type I alpha 1 gene (COLIA1) have been associated with reduced BMD in postmenopausal and thalassemia and predispose women to osteoporotic fractures." (PMID 22924029, 2012).
urothelial bladder cancer (4 papers, 2015 to 2024). "Nuclear VDR expression has also been associated with better overall survival in lung and urothelial bladder cancer patients." (PMID 38666921, 2024). "Urothelial bladder cancer progression and decrease of overall survival were linked with a reduction in VDR expression." (PMID 26501255, 2015). "Next, we analyzed the VDR levels in relation to overall survival (OS) of urothelial bladder cancer patients." (PMID 26501255, 2015). "Comparison of overall survival (OS) time in pTa-pT4 urothelial bladder cancer patients in relation to vitamin D receptor (VDR) expression (log-rank Mantel–Cox test)." (PMID 26501255, 2015). "The VDR was consistently expressed in normal epithelial cells with variable expression in urothelial bladder cancer cells." (PMID 26501255, 2015). "VDR expression can also be a potential prognostic marker in urothelial bladder cancer patients." (PMID 26501255, 2015). "In summary, VDR and CYP27B1 expression was down-regulated in urothelial bladder cancers in comparison to normal tissue." (PMID 26501255, 2015). "In conclusion, expression of the VDR and CYP27B1 are deregulated in urothelial bladder cancers." (PMID 26501255, 2015). "Therefore, the aim of this study was to evaluate the relationship between expression of the VDR and CYP27B1 and prognostic markers (such as tumor advancement, presence of metastases, tumor grade, mitotic activity, non-classic differentiation) in urothelial bladder cancer and its clinical outcome." (PMID 26501255, 2015).